ENSG00000276991
Gene: Miscellaneous RNA gene on chromosome 22 (26,673,254 to 26,673,630, forward strand). Ensembl gene ENSG00000276991.
Gene Ontology:
Biological process: cell fate specification
Cellular component: nucleus